CD14 (CD14 molecule)
Diseases named in the same sentence as CD14 in open-access papers (continued):
Sharing a sentence is not in itself a finding about the gene and the disease.
Sepsis (continued). "In this study, by integrating the results of SMR analysis and single‐cell RNA‐seq analysis, we have revealed that LGALS9 is expressed at lower levels in sepsis patients compared to healthy controls, and that low expression of LGALS9 promotes the activation and differentiation of CD14+ monocytes." (PMID 39044269, 2024). "In the context of sepsis, three monocyte subsets (CD14++CD16+, CD14+CD16++, and CD14++CD16–) were isolated from patients in the early phase of severe sepsis or septic shock.The levels of CD14++CD16+ monocytes (pro-inflammatory phenotype) were positively correlated with the disease severity scores." (PMID 37962697, 2024). "This may be one of the factors related to the prognostic value of M-MDSCs in sepsis, when CD14+ cells (M-MDSCs) were depleted, CD4+ and CD8+ T cells in patients with sepsis proliferated rapidly." (PMID 38609858, 2024). "Overall, our research demonstrated a significant correlation between the prevalence of CD14+ CD16+ monocytes and the severity of sepsis, suggesting that their increased presence may serve as an indicator of a more severe manifestation of the condition." (PMID 39076981, 2024). "By transcriptome analysis, we found that the macrophage marker CD14 was less up-regulated in SIRS than bacterial and viral infections and a higher macrophage M0/Tregs ratio could distinguish SIRS from other types of sepsis." (PMID 38053180, 2023). "In the validation cohort, non-CRRT group, the level of serum CD14 in sepsis patients on the 7th day after treatment was significantly lower than that in 24 h after admission in PICU." (PMID 36650427, 2023). "In vivo, the CD14 + CD16 + + monocyte population expands during infections, especially in sepsis." (PMID 36721090, 2023). "Notably, pDC B, characterized by high expression of S100A8, S100A9, FCN1 and CD14, was the dominant subtype in the ICU-Sepsis group." (PMID 37781404, 2023). "Unlike the other two CD14+ subpopulations, we found a higher proportion of the non-classical subset in all sepsis patients with diabetes compared to non-diabetic patients." (PMID 36687421, 2022). "Patients with sepsis-related ARDS had significantly higher numbers of CD14+/CD81+ monocyte-derived BAL EV than patients with sepsis without ARDS (P = 0.015)." (PMID 35234046, 2022). "Thus, CD14+/CD81+ BAL EVs are a potential biomarker for disease severity and mortality in sepsis-related ARDS." (PMID 35234046, 2022). "CD206+ EV numbers were unchanged in patients with sepsis-related ARDS (CD206 being an alveolar macrophage marker), indicating that the increased CD14+ EV observed in patients with ARDS were derived from infiltrating monocytes as opposed to resident alveolar macrophages." (PMID 35234046, 2022). "In the absence of diabetes and obesity, the negative impact of sepsis including septic shock on CD14+ and CD33+ monocytes were more moderate (ds = −0.3 to −0.8) when compared with obese diabetic patients (ds = −1.0)." (PMID 36687421, 2022). "Regarding sepsis and diabetes, the CD14+CD16– subset was affected most in non-obese but not in obese patients." (PMID 36687421, 2022). "In this study, patients with sepsis-related ARDS had significantly higher numbers of CD14+/CD81+ BAL EV than patients with sepsis without ARDS." (PMID 35234046, 2022). "Thus, CD14+ BAL EV are a potential biomarker for disease severity and mortality in sepsis-related ARDS." (PMID 35234046, 2022). "Characterization studies showed that a greater number of monocyte-derived CD14+/CD81+ EV were present in the BAL of patients with sepsis-related ARDS compared to patients with sepsis without ARDS (medians 1.23 × 108/mL vs. 6.26 × 107/mL, P = 0.015)." (PMID 35234046, 2022). "From the available serum biomarkers for the diagnosis of sepsis, CRP, PCT, CD14, suPAR and other biomarkers showed good correlations for the diagnosis and treatment of sepsis, but their specificity and sensitivity are still not ideal for the diagnostic efficacy." (PMID 34565302, 2021).
Sepsis (continued). "A difference was shown in MFI HLA-DR on both CD14+High and CD14+Low monocytes between sepsis and non-septic SIRS patients (0.9 vs. 1.5, p = 0.05; and 2.9 vs. 4.2, p = 0.05 respectively)." (PMID 34945111, 2021). "Despite the fact that the P2X7 receptor induces the release of CD14, it is not known if P2X7 contributes to the extracellular pool of CD14 during infection or what its role is in defending the host during sepsis." (PMID 33135636, 2020). "In sepsis induced by Gram-negative bacteria, LPS from Gram-negative bacteria, CD14, and TLR4 form a complex to activate several intracellular signaling pathways including NF-κB, MAPKs (such as p38), JNK, and Erk." (PMID 32889432, 2020). "Therefore, we prospectively analyzed the gene expression profile of circulating CD14+ monocytes from healthy volunteers (n = 54) and intensive care unit (ICU) patients (n = 76), of which n = 36 had sepsis." (PMID 31906585, 2020). "Circulating CD14 has been found at elevated levels in sepsis, but the exact mechanism of CD14 release in sepsis has not been established." (PMID 33135636, 2020). "We found that activation of α7 nAChR on macrophages affects the expression of membrane proteins, such as HLA-DR, CD14, CD11b, and CD54, and also induces changes in the IL-10 production, all being involved in immunosuppression and hyperinflammation during sepsis." (PMID 32230846, 2020). "Basal levels of CD14++CD16+ but not CD14+CD16++ monocytes were significantly elevated in severe sepsis and septic shock." (PMID 28446249, 2017). "Coculture with ASCs for 24 h significantly reduced the expression of CD14++CD16+ cells in patients with severe sepsis and septic shock (18.8% vs 13.0%, p < 0.001), but not in healthy volunteers (7.2% vs 7.5%, p > 0.05)." (PMID 28446249, 2017). "In comparison with non-severe sepsis cases, higher frequencies of TLR4+896A/G and CD14-159C/T variant alleles were noted in severe sepsis cases." (PMID 27861595, 2016). "In addition to LPS, several endogenous danger-associated molecular patterns (DAMPs), including the newly identified peroxiredoxin-1 (Prdx1), can also interact with CD14/TLR4 and elicit severe sepsis-like response." (PMID 27142532, 2016). "Thus, interfering with LBP/CD14 interactions has been considered for treating endotoxin-induced diseases, such as ARDS and sepsis." (PMID 25025695, 2014). "Fourth, given the number of DNA banks and ease of examining a large number of polymorphisms in a genetic association study, there is a possibility that such negative analyses of CD14-159C/T and sepsis have not been published." (PMID 23990939, 2013). "We suggest that CD14 and TLR2 are a key factor in monocyte hyporesponsibility during severe sepsis." (PMID 19371402, 2009). "Our findings are limited by missing data about levels of PDE4 (or PDE4 activity) in CD14+ monocytes from control subjects and patients with sepsis; these data would strengthen the conclusion that inhibition of PDE4 activity is a potential treatment for sepsis." (PMID 19091080, 2008). "To determine the effect of B. pseudomallei sepsis on TLR protein expression at the surface of peripheral blood cells, we compared the expression of CD14, TLR1, TLR2, and TLR4 on circulating monocytes and granulocytes of patients with melioidosis and healthy controls using FACS analysis." (PMID 17676990, 2007). "Individually, higher frequency of CD15+CD14+monocytes [0.83 (95%CI 0.71,0.94)], CD45RA-CX3CR1+CTLA4+CD4+ T cells [0.77 (95%CI 0.64,0.90)], CD45RA−17A+CD4+ T cells [0.76 (95% CI 0.61,0.90)], and Ki67+ B cells [0.76 (95%CI 0.64, 0.88)] yielded good AUROC for distinguishing sepsis from healthy." (PMID 40433376, 2025). "We further compared the infiltration differences of each cell type between the sepsis group and the control group using the Wilcoxon test (P < 0.05), and found that there were significant differences in CD4+ memory cells, B cells, CD16+ and CD14+ monocytes, and CD8+ T cells between the two groups." (PMID 41246299, 2025).
Sepsis (continued). "Additionally, we found the miR-155-5p level were considerably higher in CD14+ monocytes of pneumonia-induced sepsis patients than that of pneumonia patients without sepsis and healthy people." (PMID 36923408, 2023). "Additionally, SHIP1 expression was markedly diminished in CD14+ monocytes of pneumonia-induced sepsis patients compared with that of pneumonia patients without sepsis and healthy people." (PMID 36923408, 2023). "We observed a marked and significant decrease in small CD9+CD14+ and CD9+CD61+ EVs 7 days post-trauma compared with 24-h values in patients who did not develop any post-trauma complications such as systemic inflammatory response syndrome (SIRS), acute respiratory distress syndrome (ARDS), or sepsis." (PMID 38035093, 2023). "Previous prospective trials of inhibitors or antibodies to gene products linked to sepsis, such as IL1RN, CD14, and tissue factor, failed to have benefit, suggesting that these genes are only a small part of a polygenic disease; blocking only this small part would have little overall effect." (PMID 35275946, 2022). "However, among non-diabetic sepsis patients, CD14 levels on the CD14+CD16– subset were decreased when compared to diabetic patients." (PMID 36687421, 2022). "In addition, the CD14 MFI of monocytes demonstrated a significant difference in children with sepsis but did not affect the disease outcome." (PMID 36010061, 2022). "Furthermore, our data confirmed previous reports in that circulating CD14 expression densities were elevated in non-infected diabetes as well as in sepsis patients." (PMID 36687421, 2022). "Therefore, circulating CD14 is not only a marker for sepsis but also an important component of the host’s innate immune system because the P2X7 receptor releases it in a regulated manner in order to control infection and increase survival during sepsis." (PMID 33135636, 2020). "As a result, in the past decades, attention has been directed to different sepsis biomarkers other than the conventional parameters; these biomarkers include leukocyte cell surface antigens such as nCD64, CD14, CD11b, CD163, and soluble CD14 subtype (presepsin)." (PMID 33204274, 2020). "Also, we found that during a murine model of sepsis, P2X7 receptor activity is important for maintaining elevated levels of CD14 in biological fluids and a decrease in its activity results in higher bacterial load and exacerbated organ damage, ultimately leading to premature deaths." (PMID 33135636, 2020). "We sought to analyze the whole transcriptome of the major monocyte subpopulation and therefore isolated CD14+ monocytes (corresponding to the classical and intermediate subpopulations) from the whole blood of randomly selected patients with sepsis, without sepsis, and healthy individuals." (PMID 31906585, 2020). "The disruption of TLR signaling pathway induced by live virulent E. coli and E. coli-derived LPS in pigs by CD14 neutralization antibodies resulted in decreased levels of pro-inflammatory cytokines IL-1β, IL-6, IL-8, and TNF-α, and lower granulocyte activation in a pig model of sepsis." (PMID 31847111, 2019). "However, in a previous study, we could demonstrate specific changes in histone modifications and found sepsis-induced alterations in both MHC-II locus and CIITA gene of isolated CD14++ CD16—monocytes." (PMID 30212590, 2018). "In addition, after in vitro LPS stimulation, CD14++ CD16- monocytes impress by producing a broad range of different cytokines including CC-chemokine ligand 2 (CCL2) and interleukin (IL) 10 and seem to be relevant in the initial sepsis-induced immune response." (PMID 30212590, 2018). "With the presented results in this study, demonstrating that LPS-activated tolerant CD14+ monocytes upregulate IL7R on the cell surface, it can be speculated that IL-7 administration during sepsis will also affect the IL7R-positive tolerant monocyte population." (PMID 28404994, 2017).
Sepsis (continued). "In line with previous findings, eritoran and anti-CD14 mostly inhibited Gram-negative-induced inflammation, whereas Gram-positive inflammation was more complement dependent, possibly explaining the lack of effects of eritoran in a broad sepsis population." (PMID 27581539, 2017). "Commercial methods for the automated measurement of the soluble CD14 subtype presepsin (sCD14-ST) and lipopolysaccharide binding protein (LBP), the two old biomarkers, have been proposed over the past years to manage critically ill newborns with acute inflammation and sepsis." (PMID 26063982, 2015). "Furthermore, this subset of non-classic (CD14+CD16++) monocytes is expanded in sepsis patients, and also in SLE." (PMID 25485543, 2014). "As we used a model of polymicrobial (gram-positive and-negative) sepsis, changes in CD14 expression, increased by TLR4- and/or TLR2-mediated signaling, may reflect infection with both gram stain groups." (PMID 23302299, 2013). "As shown in our study, an inadequate downregulation of TLR2 and CD14 (and consecutive reduced cytokine release) during sepsis might have a negative influence on outcome." (PMID 19371402, 2009). "Interestingly we could show in our study a relatively lower receptor expression (CD14, TLR2 and as a trend in TLR4), in patients with sepsis that died, compared to patients that survived." (PMID 19371402, 2009). "Taken together, these data suggest that a reduced TLR2 and CD14 expression during sepsis might have a negative outcome in sepsis." (PMID 19371402, 2009). "Additionally, soluble CD14 (sCD14-ST) and PCT were also identified as significant predictors (p = 0.045 and p = 0.044, respectively), supporting their diagnostic relevance in distinguishing sepsis from non-infectious systemic inflammation." (PMID 41153764, 2025). "However, there have been no reports of CD14+ monocytes pyroptosis in clinical patients with sepsis." (PMID 36923408, 2023). "The results showed that the expression of SLAMF7 in CD11b+CD14+ monocytes, but not CD3+ T cells, was significantly increased in patients with sepsis (n = 83) compared with expression levels in healthy donors (n = 81)." (PMID 36749634, 2023). "Therefore, the effect of CaD to decrease CD14 and TLR4 expression could offer one mechanism to explain why CaD inhibits NF-κB and suppresses the release of downstream NF-κB activation products—TNFα, IL-1β, IL-6, and MCP-1 in animal models of sepsis and diabetic nephropathy and retinopathy." (PMID 34829669, 2021). "In a first unbiased approach, we therefore isolated CD14+ monocytes from ICU patients with and without sepsis, respectively, as well as healthy donors, and comprehensively analyzed their transcriptome by RNA sequencing." (PMID 31906585, 2020). "The frequency of PMN-MDSCs (SSChigh CD16+ CD15+ CD33+ CD66bhigh CD114+ CD11b+/low LDG) and M-MDSCs (SSClow CD14+ CD11b+ CD16− CD15+) does not differ between non-infectious critical ill patients and sepsis patients." (PMID 30873175, 2019). "The levels of CD14++CD16+, CD14+CD16++, and CD14++CD16– monocytes in the early phase of severe sepsis and septic shock were determined with or without coculture of ASCs." (PMID 28446249, 2017). "In previous work, our group has used scRNA-seq to profile circulating peripheral blood mononuclear cells (PBMCs) in urosepsis, identifying a unique CD14+ monocyte subtype (monocyte substate 1, or MS1), that is expanded in sepsis relative to infection without sepsis." (PMID 39371152, 2024). "There may be no magic target to cure sepsis, and a combined approach could be more beneficial than targeting a single molecule, as shown for IL‐1 and IL‐18 in murine sepsis, IL‐1 and TNF in a rat model, or CD14 and factor XIa in rabbits." (PMID 32176432, 2020).
melanoma (139 papers, 2001 to 2026). A malignant, usually aggressive tumor composed of atypical, neoplastic melanocytes. "The presence of tumor-associated CD1c+CD14+ DCs has been reported in multiple studies including melanoma, breast cancer, ovarian cancer, and head and neck cancer." (PMID 38242119, 2024). "The role of monocytes in the response to immunotherapy has found correlation in melanoma where the number of CD14+CD16−HLA-DRhigh monocytes has been associated with better response to ICI therapy." (PMID 36203609, 2022). "CD14+ HLA-DR+ CD16- monocytes were associated with the response to checkpoint therapy in melanoma patients." (PMID 35625643, 2022). "Namely, the dedifferentiated MITFlow/c-Junhigh melanoma phenotype in human melanoma samples, was associated with increased infiltration by myeloid immune cells, as assessed by CD14 immunohistochemistry." (PMID 35432344, 2022). "For instance, higher percentages (>11%) of circulating CD14+ M-MDSCs independently predicted the risk of death in stage III/IV melanoma patients." (PMID 34336860, 2021). "A low frequency of CD14+CD11b+HLA-DR−/low MDSC has been previously associated with survival in patients with advanced melanoma." (PMID 29973204, 2018). "We found that MITFlow/c-JUNhigh melanomas have high levels of the myeloid cell transcripts CSF1R or CD14, arguing that in particular myeloid cell infiltrates are associated with this melanoma phenotype." (PMID 26530832, 2015). "In prostate cancer and melanoma patients, increased levels of CD14+CD11b+HLA-DRlow/− M-MDSCs have been associated with poor immune response to an antitumor vaccine." (PMID 25436215, 2014). "Furthermore, the CD14+ monocyte subset was implicated in a favorable response to ICB among melanoma patients." (PMID 39026661, 2024). "Furthermore, CD14+ monocytes can suppress the action of T cells, associated with poor outcomes in melanoma patients." (PMID 38600248, 2024). "Inhibition of STAT3 and MAPK may promote the differentiation of CD14+ cells into moDCs and this was associated with an increase in the infiltration of effector T-cells (with a Th1 profile) in melanoma." (PMID 37190135, 2023). "Western blot analysis further showed that the hNVs contained specific protein markers of individual NVs, including CD61, an important marker for platelet adhesion and activation; CD14, an endotoxin receptor on macrophages; and Melan-A, a melanoma tumor-associated antigen." (PMID 32999291, 2020). "Moreover, they express higher levels of TAM-related markers (CD206, MerTK and CD163), compared to blood circulating CD14+ DCs, we previously linked to lower immunological response to DC-based vaccines in melanoma patients." (PMID 32488012, 2020). "For stage III and IV melanoma patients receiving CD1c+ DC-based vaccinations, the presence of CD1c+CD14+ DCs (DC3) in vaccine preparations suppresses CD4+ T cells." (PMID 40789452, 2025). "Altogether, our work provides new insights in processes at the protein level that affect the protumor and immunostimulatory capability of melanoma-induced CD14+ DC3s." (PMID 40789452, 2025). "Here, we characterized by tandem LC-MS/MS the proteomic changes in conventional DCs during their transition into CD14+ ti-DC3s in vitro, using conditioned medium from the melanoma cell line BLM." (PMID 40789452, 2025). "Microvesicles from stage IV melanoma patients had similar effects on CD14+ monocytes, directing their differentiation into CD14+HLA-DR/low cells that displayed TGF-β-mediated suppressive functions on T-cell activities." (PMID 40443670, 2025). "From the diagnostic point of view, identification of the easily accessible subset CD14+CD16+ of monocytes offers a valuable tool for melanoma patient stratification in HMOX1 levels to predict patient survival." (PMID 41109135, 2025). "On the other hand, monocytes present in the melanoma stroma (stromal CD14+— sCD14+) presented a transcriptional pattern different from iCD14+ cells." (PMID 39126091, 2024).